BARD1 (BRCA1 associated RING domain 1)
Description:
E3 ubiquitin-protein ligase. The BRCA1-BARD1 heterodimer specifically mediates the formation of 'Lys-6'-linked polyubiquitin chains and coordinates a diverse range of cellular pathways such as DNA damage repair, ubiquitination and transcriptional regulation to maintain genomic stability. Plays a central role in the control of the cell cycle in response to DNA damage. Acts by mediating ubiquitin E3 ligase activity that is required for its tumor suppressor function. Also forms a heterodimer with CSTF1/CSTF-50 to modulate mRNA processing and RNAP II stability by inhibiting pre-mRNA 3' cleavage.
Tractability: Small molecule: it has a binding pocket of medium quality. PROTAC: UniProt records ubiquitination sites on it; ubiquitination databases record sites on it.
Gene: Protein-coding gene on chromosome 2 (214,725,646 to 214,809,707, reverse strand). Ensembl gene ENSG00000138376.
Subcellular location: Nucleus
Subcellular location (Human Protein Atlas): Nuclear speckles; Nucleoplasm; Cytoplasmic bodies
Pathways (Reactome):
DNA Repair: HDR through Homologous Recombination (HRR); HDR through Single Strand Annealing (SSA); Homologous DNA Pairing and Strand Exchange; Nonhomologous End-Joining (NHEJ); Presynaptic phase of homologous DNA pairing and strand exchange; Processing of DNA double-strand break ends; Recruitment and ATM-mediated phosphorylation of repair and signaling proteins at DNA double strand breaks; Resolution of D-loop Structures through Holliday Junction Intermediates; Resolution of D-loop Structures through Synthesis-Dependent Strand Annealing (SDSA)
Disease: Defective DNA double strand break response due to BARD1 loss of function; Defective DNA double strand break response due to BRCA1 loss of function; Defective HDR through Homologous Recombination Repair (HRR) due to PALB2 loss of BRCA1 binding function; Defective HDR through Homologous Recombination Repair (HRR) due to PALB2 loss of BRCA2/RAD51/RAD51C binding function; Defective homologous recombination repair (HRR) due to BRCA1 loss of function; Impaired BRCA2 binding to PALB2; Impaired BRCA2 binding to RAD51
Metabolism of proteins: Metalloprotease DUBs; UCH proteinases
Cell Cycle: G2/M DNA damage checkpoint
Gene Ontology:
Molecular function: protein binding; protein heterodimerization activity; protein homodimerization activity; RNA binding; ubiquitin-protein transferase activity; histone H2AK127 ubiquitin ligase activity; histone H2AK129 ubiquitin ligase activity; kinase binding; ubiquitin protein ligase activity; ubiquitin-modified histone reader activity
Biological process: cellular response to ionizing radiation; negative regulation of apoptotic process; negative regulation of protein export from nucleus; positive regulation of apoptotic process; protein K6-linked ubiquitination; regulation of phosphorylation; chromatin remodeling; DNA damage response; DNA repair; DNA strand resection involved in replication fork processing; homologous recombination; mitotic G2/M transition checkpoint; negative regulation of cell cycle; negative regulation of mRNA 3'-end processing; positive regulation of protein catabolic process; protein ubiquitination; regulation of cell cycle; regulation of DNA damage checkpoint; regulation of DNA repair; regulation of transcription by RNA polymerase II; tissue homeostasis
Cellular component: BRCA1-A complex; BRCA1-B complex; BRCA1-BARD1 complex; BRCA1-C complex; cytoplasm; nuclear speck; nuclear ubiquitin ligase complex; nucleoplasm; nucleus; ubiquitin ligase complex
Genetic constraint (gnomAD): Loss-of-function variants: 64 observed, 72.46 expected, observed/expected ratio (o/e) 0.88, 90% interval 0.72 to 1.09. The upper end of that interval is the gene's LOEUF score, 1.09, which puts it in group 4 of 6, group 1 being the genes least tolerant of losing a copy. Missense variants: 967 observed, 952.94 expected, observed/expected ratio (o/e) 1.01, 90% interval 0.96 to 1.07. Synonymous variants: 378 observed, 341.79 expected, observed/expected ratio (o/e) 1.11, 90% interval 1.02 to 1.2.
Gene-disease validity (ClinGen):
ClinGen rates the evidence that BARD1 causes each of these diseases.
BARD1-related cancer predisposition (autosomal dominant): Definitive. Hereditary cancer predisposition due to variation(s) in the BARD1 gene.
familial ovarian cancer (autosomal dominant): Disputed. An instance of ovarian cancer that is caused by an inherited modification of the individual's genome.
Cancer hallmarks: proliferative signalling (promotes); escaping programmed cell death (promotes); genome instability and mutations (promotes); escaping programmed cell death (suppresses); suppression of growth (promotes); invasion and metastasis (suppresses); genome instability and mutations (suppresses)
Homologues: Orthologues: chimpanzee BARD1 (99% identical), macaque BARD1 (95% identical), pig BARD1 (85% identical), dog BARD1 (82% identical), rabbit BARD1 (77% identical), mouse Bard1 (70% identical), rat Bard1 (69% identical), guinea pig BARD1 (65% identical), tropical clawed frog bard1 (45% identical), zebrafish bard1 (29% identical), Drosophila melanogaster CG7457 (21% identical), Caenorhabditis elegans T16G1.9 (14% identical).
Diseases named in the same sentence as BARD1 in open-access papers:
BARD1 is named in the same sentence as 116 diseases in open-access papers, as found by Europe PMC text mining. Sharing a sentence is not in itself a finding about the gene and the disease. The quoted sentences say what the papers report.
breast cancer (210 papers, 2005 to 2026). A primary or metastatic malignant neoplasm involving the breast. "Carriers of pathogenic BARD1 variants are assumed to have an at least twofold increased lifetime risk of breast cancer compared with the general population." (PMID 41528496, 2026). "The BARD1 gene was incorporated into the TruRisk® gene panel of the GC-HBOC in recent years as a moderate-risk gene for breast cancer." (PMID 41528496, 2026). "Case–control studies have found a low to moderate association between breast cancer and pathogenic and likely pathogenic (P/LP) variants in the BARD1 gene, with a prevalence range of 0.1% to 0.51% in patients with breast cancer." (PMID 40805222, 2025). "We demonstrated that the mutation frequency rates of BARD1 were 0.45% among high-risk breast cancer patients and 0.29% among ovarian cancer patients." (PMID 40805222, 2025). "We showed that LoF missense variants in the ARD and BRCT domains are enriched in breast cancer cohorts, thereby linking the specific molecular functions of these domains to BARD1 tumor suppression in humans." (PMID 41282735, 2025). "While germline BARD1 variants have been associated with an increased risk of breast cancer, the evidence supporting risk-reducing mastectomy for BARD1 carrier’s remains limited." (PMID 40800071, 2025). "It found that BARD1 mutations occurred in 0.45% of breast cancer cases and 0.29% of ovarian cancer cases." (PMID 40805222, 2025). "An example of this is when a patient with breast cancer had a germline BARD1 deletion or loss of heterozygosity in the tumor, resulting in a basal-like gene expression profile similar to those observed in cancers associated with BRCA1 germline PVs." (PMID 40805222, 2025). "Protein-truncating variants in established susceptibility genes BRCA2, BRCA1, CHEK2, PALB2, ATM and MAP3K1 were associated with a risk of breast cancer, while BARD1 and ATRIP met exome-wide significance for the first time." (PMID 41044259, 2025). "In a meta-analysis, the mutation frequency rates in the BARD1 gene among breast cancer and ovarian cancer patients from mixed populations were 0.25% and 0.12%, respectively." (PMID 40805222, 2025). "Evaluating the cancer risk and clinical significance of BARD1 mutations in the local Chinese patients with breast cancer, ovarian cancer, or both is clinically important for designing an appropriate surveillance scheme." (PMID 40805222, 2025). "BARD1 variants are associated with hereditary breast cancer and neuroblastoma, yet, 98% of missense variants remain variants of uncertain significance (VUS)." (PMID 41282735, 2025). "We found LoF missense variants in BARD1’s structured domains were enriched in breast cancer cases with an odds ratio of 1.73 (95% CI 1.14 – 2.63) and all LoF missense BARD1 variants were enriched in breast cancer cases with an odds ratio of 1.72 (1.19 – 2.48)." (PMID 41282735, 2025). "Another example is BRCA1-associated RING domain 1 (BARD1) in breast cancer, which is a low-penetrance gene with an unclear clinical relevance, partly because of limited functional evidence." (PMID 40282361, 2025). "Many studies have widely discussed the association of the BARD1 missense mutation c.1670G>C; p.(Cys557Ser) to breast cancer risk." (PMID 40805222, 2025). "With SGE able to accurately predict cancer risk and enrichment of LoF BARD1 missense variants in breast cancer cases, we provide additional evidence that BRCA1 and BARD1’s role in HDR is required for tumor suppression in humans." (PMID 41282735, 2025). "The p.Glu652fs mutation in the BARD1 gene leads to the loss of the functional BRCT domain of the BARD1 protein, highlighting the association between BARD1 mutations and an increased risk of breast cancer." (PMID 39996778, 2025). "For instance, beyond the well-known BRCA mutations in breast cancer, alterations in genes such as BARD1, and pathogenic variants of RAD51C and RAD51D, reported to be associated with increased breast cancer risk, have also been identified." (PMID 40723883, 2025).
breast cancer (continued). "To identify alternative mechanisms of PARPi resistance, we generated orthotopic allografts using tumor cells derived from genetically engineered mouse models (GEMMs) of Brca1- or Bard1-deficient breast cancer." (PMID 38956205, 2024). "For example, another point mutation in OLA1 (E168Q) prevents it from forming a complex with BRCA1 and BARD1 and is associated with poor outcomes in breast cancer." (PMID 38889130, 2024). "Germline variants in BARD1 exhibited a higher risk of 2- to 4-fold to develop breast cancer as compared to population-based risk, but there is insufficient evidence for RRM." (PMID 38397209, 2024). "A point mutation (E168Q) in the OLA1 gene is linked to apoptosis, preventing the formation of a complex with BRCA1 and BARD1, and is associated with poor outcomes in breast cancer." (PMID 38889130, 2024). "We show that FLT1 is activated in the tumor cells of PARPi-resistant tumors from Brca1- and Bard1-deficient models as well as from breast cancer patients." (PMID 38956205, 2024). "The BARD1 gene has been recently established as a moderate risk gene for hereditary breast cancer, particularly in triple-negative breast cancer." (PMID 36709314, 2023). "BARD1 (BRCA1-associated RING domain 1) is an essential gene related to breast cancer development that encodes a protein that interacts with the N-terminal region of BRCA1." (PMID 36765720, 2023). "These SNPs revealed low penetrance effects in the BARD1 gene on breast cancer predisposition with a remarkable reduction in breast cancer risk." (PMID 35650591, 2022). "A direct sequencing and SNaPshot analysis was used to identify the exon mutation of the BARD1 gene in 60 early-onset breast cancer cases and 240 healthy controls." (PMID 35650591, 2022). "A study of 4,469 patients with breast cancer in Germany revealed 23 (0.51%) with BARD1 loss-of-function (LOF) variants as compared with 0.1% with LOF variants in controls." (PMID 36187937, 2022). "A Chinese case- control study of 507 breast cancer cases and 539 matched controls showed the effect of three non-synonymous polymorphisms in the BARD1 gene (Pro24Ser, Arg378Ser, and Val507Met) was evaluated." (PMID 35650591, 2022). "A new murine model of breast cancer with spontaneous metastases has been developed recently by orthotopic injection of Bard1-deficient breast cancer cells that spontaneously metastasize to the lung." (PMID 35994202, 2022). "Mutations in breast cancer type 1 susceptibility protein (BRCA1) and its heterodimeric binding partner BRCA1-associated RING domain protein 1 (BARD1) confer a high risk for the development of breast cancer." (PMID 35408841, 2022). "Pathogenic germline BARD1 variants provide a moderate risk for heritable breast cancer and have also been reported in pediatric patients diagnosed with high-risk neuroblastoma." (PMID 36187937, 2022). "For example, nonsynonymous BARD1 gene variants were previously reported to be associated with increased breast cancer risk." (PMID 35185591, 2022). "Thirty-seven loss-of-function variants (30 distinct variants) were found in 36 breast cancer patients, one of whom carried both BARD1:c.1921C>T and BRCA2:c.3860delA." (PMID 35353237, 2022). "A deletion mutation was identified at the rs28997575 site of BARD1 and showed an elevated risk of breast cancer by 3.4 times (P = 0.013) compared to the unaffected group." (PMID 35650591, 2022). "These PVs of BARD1 showed a moderate risk of breast cancer (odds ratio (OR) = 2.90, 95% CIs:2.25–3.75, p < 0.0001) but not ovarian cancer (OR = 1.36, 95% CIs:0.87–2.11, p = 0.1733)." (PMID 35650591, 2022). "Aside from breast cancer, BARD1 gene polymorphism was also demonstrated in neuroblastoma (NB) cases." (PMID 35650591, 2022). "The role of BARD1 Cys557Ser varient or BARD1 haplotypes as modifiers of BRCA1/2 associated breast cancer risk was further evaluated in a cohort of 5546 BRCA1 and 2865 BRCA2 mutation carriers." (PMID 35650591, 2022).
breast cancer (continued). "Among genes with a moderate risk of breast cancer, most (83.3%, n = 5/6) had published management guidelines, with the remaining moderate-risk gene (BARD1) associated with potential eligibility for a clinical trial." (PMID 35626031, 2022). "Here, through an image-based high-content RNA interference (RNAi) screen, we identified an SSL interaction between CtIP and BARD1, a low-to-moderate breast cancer risk gene, whose mutations have been associated with the development of many types of tumors." (PMID 35203293, 2022). "This pointed to a new avenue in the treatment of breast cancer by using the BARD1 gene as a potential therapeutic and diagnostic target." (PMID 35650591, 2022). "The patient in whom the pathogenic ATM variant and the BARD1 variant of uncertain significance were detected had breast cancer at the age of 39 and ovarian cancer at the age of 48." (PMID 34680878, 2021). "An essential role in regulating microtubule nucleation in breast cancer is played by γ-tubulin ubiquitylation by the BRCA1 (breast cancer type 1 susceptibility protein)/BARD1 (BRCA1-associated RING domain protein 1) E3 ligase complex." (PMID 34830792, 2021). "Germline variants in ATM, BRCA1, BRCA2, CHEK2, and PALB2 were associated with a high risk of breast cancer; a more modest risk was associated with BARD1 and RAD51C." (PMID 34445631, 2021). "A recent multicenter association study of more than 113,000 women found that protein-truncating variants in BARD1 were significantly associated with breast cancer, and most strongly with ER-negative and triple-negative disease." (PMID 34771713, 2021). "This and other data suggest that BARD1 variants confer a low-moderate risk of breast cancer susceptibility." (PMID 34771713, 2021). "PARGi is also synthetically lethal in BRCA1, BRCA2, PALB2, FAM175A and BARD1 deficient breast cancer cells." (PMID 33674744, 2021). "In the current study, we also analyzed the frequency of BARD1 variants in prostate cancer patients with relatives with breast cancer." (PMID 34771627, 2021). "Most recent, large association analysis of approximately 110,000 women performed by Breast Cancer Association Consortium provided evidence of an association between truncating BARD1 mutation and an elevated risk of breast cancer." (PMID 34771627, 2021). "Contrarily, some studies have been unable to detect a significant association of BARD1 with breast cancer risk." (PMID 33498765, 2021). "In that study, the authors identified 62 carriers of truncating BARD1 mutations in 58,728 women with breast cancer compared to 32 carriers in 52,976 controls (OR = 2.09; 95% CI, 1.35 to 3.23; p = 0.0001)." (PMID 34771627, 2021). "For the clinical management of GPV carriers of ATM, CHEK2, or BARD1, all of which are autosomal dominant, it is recommended to perform imaging screenings for preventive risk management against breast cancer." (PMID 35008774, 2021). "Pathogenic BARD1 variants also lead to increased risk for Ewing sarcoma, osteosarcoma, and neuroblastoma, in addition to an increased risk for breast cancer." (PMID 34680878, 2021). "Here, we generated a cachexia‐associated breast cancer metastasis model using murine breast cancer cells from the Bard1‐deficient, genetically engineered mouse model." (PMID 32730698, 2020). "Due to the pronounced role of BRCA1 and BRCA2 in hereditary breast and ovarian cancer, different mutations and variants of BARD1 were first investigated in breast cancers and various gynecological cancers in the late 1990s and early 2000s." (PMID 32708251, 2020).